CCDC160 (coiled-coil domain containing 160)
Tractability: PROTAC: ubiquitination databases record sites on it.
Gene: Protein-coding gene on chromosome X (134,237,047 to 134,246,842, forward strand). Ensembl gene ENSG00000203952.
Homologues: Orthologues: chimpanzee CCDC160 (99% identical), macaque CCDC160 (93% identical), dog CCDC160 (76% identical), pig CCDC160 (69% identical), rabbit CCDC160 (69% identical), rat Ccdc160 (59% identical), mouse Ccdc160 (59% identical), tropical clawed frog ccdc160 (26% identical), Drosophila melanogaster vvl (15% identical), Caenorhabditis elegans ceh-18 (14% identical), Drosophila melanogaster acj6 (9% identical), Caenorhabditis elegans unc-86 (8% identical). Paralogues in human: POU3F4 (16% identical), POU2F1 (15% identical), POU3F2 (15% identical), POU2F2 (14% identical), POU3F1 (14% identical), POU3F3 (14% identical), POU2F3 (14% identical), POU5F1 (12% identical), POU5F1B (12% identical), POU1F1 (12% identical), POU4F3 (11% identical), POU6F2 (11% identical), and 5 more.
Diseases named in the same sentence as CCDC160 in open-access papers:
CCDC160 is named in the same sentence as 2 diseases in open-access papers, as found by Europe PMC text mining. Sharing a sentence is not in itself a finding about the gene and the disease. The quoted sentences say what the papers report.
colon cancer (1 paper, 2024). "Currently, there is limited research on CCDC160; however, our study found that CCDC160 is positively correlated with immune cells and their functions in colon cancer, suggesting that CCDC160 may represent a novel target in this context." (PMID 39440054, 2024). "Future research could further investigate the role of CCDC160 in the pathogenesis of colon cancer." (PMID 39440054, 2024).
cancer (1 paper, 2021). A tumor composed of atypical neoplastic, often pleomorphic cells that invade other tissues. "Currently, there is no reported association between OFCC1, Syngr3, CCDC160 and cancer." (PMID 34026368, 2021).